IL15 (interleukin 15)
Diseases named in the same sentence as IL15 in open-access papers (continued):
Sharing a sentence is not in itself a finding about the gene and the disease.
COVID-19 (continued). "In our study, we first showed that despite similar respiratory severity, plasma concentrations of numerous cytokines characterizing the “cytokine storm” (i.e. IL-1β, IL-6, IL-8, IL-15, TNF-α, CCL2, CCL4, CCL19, CCL20, TGF-α) were lower in COVID-19 compared to non-COVID-19 patients." (PMID 33272291, 2020). "In contrast to COVID-19, which showed markedly elevated plasma concentrations of 11 SMs, we observed decreased levels of several SMs, mainly pro-inflammatory cytokines (e.g., IFN-γ, IFN-α2, TNF-α, IL-7, IL-17A, and IL-15) in both the remission and acute phases of TTP." (PMID 39337495, 2024). "Among patients with symptomatic COVID-19 (N = 240), hierarchical correlation matrices and force-directed network models identified two groups of strongly correlated mediators centered around IFN-α2/IFN-γ and TNF/lymphotoxin-α, respectively, with IL-15 appearing as a key inter-group mediator." (PMID 38368384, 2024). "The mediators CCL3, CCL4, CCL2, CCL5, IL-12, IL-15, IL-1Ra, and PDGF were higher in healthy volunteers, while the mediators CCL11, CXCL10, IL-1b, IL-6, TNF-a, IFN-g, IL-17, IL-9, IL-10, IL-13, FGF-basic, G-CSF, GM-CSF, IL-7, and IL-2 were increased in COVID-19 positive patients." (PMID 37903875, 2023). "Similarly, alveolar capillary endothelial cells showed strong and diffuse immunoreactivity for IL-6 and IL-15, observed as red dots in the cytoplasm, in the COVID-19 group but not in the control group (p < 0.001)." (PMID 34463916, 2022). "Furthermore, we evaluated the expression of the most important inflammatory cytokines/chemokines commonly observed in COVID-19 patients, and we found that FBA was able to reduce the expression of IL-15, MCP-1 and TNF-α in human enterocytes exposed to WT SARS-CoV-2." (PMID 35164139, 2022). "This study would suggest that IL-15 therapy may be tolerated and effective in older COVID-19 patients that may not be able to produce IL-15, however this has not been confirmed." (PMID 32655581, 2020). "First, we studied the circulating levels of IL-1α, IL-1β, IL-18, IL-15, IL-12p40, IL-12p70, IL-6, IL-27, IL-1Ra, IL-1RI, IL-1RII, IL-6R and sgp130, which are innate proinflammatory cytokines, and their receptors in survivors and non-survivors of severe COVID-19 and healthy controls." (PMID 36142255, 2022). "Indeed, defined circulating factors - CXCL8, IL-10, IL-15, IL-27, and TNF-α - positively correlate with older age, longer hospitalization, and a more severe form of the disease and may thus represent the leading signature in critical COVID-19 patients." (PMID 33159040, 2020). "In Non-SOT COVID-19 patients, we observed 6 (IL-13, IL-10, IFN-γ, IL-12p70, MCP-2, IL-6) and 9 (IL-16, IL-13, TNF-α, IL-6, IL-18, IL-15, MIP-1α, IL-2Ra, IL-8) cytokine correlations with monocyte and neutrophil derived cfDNA, respectively." (PMID 35075453, 2022). "We observed significantly increased levels of inflammatory cytokines/chemokines such as GM-CSF, IL-15, IL-6 and IL-8 in both SOT and Non-SOT COVID-19 patients who subsquently developed severe disease compared to patients with mild/moderate disease." (PMID 35075453, 2022). "Also, patients with COVID-19 were characterized by increased secretion of proinflammatory cytokines CCL20/MIP3ɑ, IL-10, IL-15, IL-27 in non-survivors than in controls." (PMID 36758022, 2023). "However, IL15, CXCL9 and IL12A levels were not significantly altered in KD or severe COVID-19 compared to FC or HC, respectively." (PMID 36159873, 2022). "Interestingly, pro-inflammatory cytokines—such as IFN-gamma, TNF, IL-23, IL-15, IL-21 and IP-10/CXCL-10—were detected both in the sera of severe ICU hospitalized and of non-hospitalized COVID-19 patients." (PMID 33019628, 2020).
COVID-19 (continued). "While IL-15 and IL-16 are clustered with neutrophil-derived cfDNA in SOTRs with COVID-19, inflammatory cytokines such as IL-15, IL-6, IL-16, and MIP-1α are clustered with total (ncfDNA) and tissue-specific cfDNA from adipocytes, monocytes, erythroblasts, and neutrophils in Non-SOT COVID-19 patients." (PMID 35075453, 2022).
melanoma (121 papers, 2006 to 2026). A malignant, usually aggressive tumor composed of atypical, neoplastic melanocytes. "Interleukin-15 (IL-15) is expressed in various cancers, including melanoma, where it exists in distinct membrane-associated isoforms." (PMID 42064067, 2026). "For example, circRNA has been used to encode cytokines such as IL-15 and IL-12 for the treatment of melanoma and liver cancer, either as standalone therapies or in combination with PD-1 antibodies 51,52." (PMID 39816687, 2025). "The importance of IL-15 in cancer-associated TRMs has also been demonstrated in melanoma, where intratumoral IL-15 expression varies among patients and shows a positive correlation with TRM abundance." (PMID 41479900, 2025). "Analyses of public datasets have shown that elevated levels of soluble IL‐15/IL‐15Rα are associated with impaired NK cell functionality in late‐stage melanoma, while high expression correlates with improved survival in stages II and III." (PMID 41085102, 2025). "MDM2 inhibitors not only promote IL-15 production by cancer-associated fibroblasts, macrophages, and B cells but also increase IL-15 production by melanoma cells, with high IL-15 expression positively correlated with mouse viability." (PMID 39263534, 2024). "Here, we investigated the anti-tumour activity of delNS1-IL-15 influenza A viruses, encoding IL-15 from the NS gene segment, in comparison to the corresponding delNS1 virus in a panel of human melanoma cell lines." (PMID 22563505, 2012). "In conjunction with the finding that gp100-specific T cells express CD122 (IL-15Ra) and require IL-15 for their pathogenic role in melanocyte destruction, IL-15 may also enhance melanoma-specific TRM maintenance." (PMID 30555481, 2018). "Transcriptomic analysis of melanoma patients revealed that high IL-15 expression correlates with immune activation, inflammation and epithelial-to-mesenchymal transition (EMT), along with coordinated upregulation of IL-15 receptor subunits." (PMID 42064067, 2026). "In melanoma, IL-15 expression positively correlates with TRM abundance and higher mRNA levels of ITGAE (CD103), ITGA1 (CD49a), and CD69, reinforcing its role in maintaining residency and effector potential." (PMID 41479900, 2025). "Intranasal administration of Neospora caninum modified to produce human IL-15 fused with IL-15Rα shows promise in treating lung metastases from melanoma." (PMID 40636453, 2025). "The novel fusion protein SON-1210, combining IL-15 and IL-12 with a human albumin-binding domain, enhances melanoma treatment by improving pharmacokinetics and targeting." (PMID 40636453, 2025). "We have previously shown inhaled IL-15 is associated with anti-tumor responses in dogs with metastatic osteosarcoma (OSA) and melanoma." (PMID 41209004, 2025). "For example, IFN-γ downregulates NKG2D ligand expression in melanoma cells which impairs NKG2D-mediated cytolysis of MHC class I-deficient melanoma by NK cells, and IL-15 can partially overcome this tumour escape mechanism." (PMID 40868162, 2025). "One promising treatment modality for dogs with metastatic OSA or melanoma is inhaled recombinant cytokine therapy using human interleukin-2 (IL-2) or interleukin-15 (rhIL-15)." (PMID 41041167, 2025). "IL-2 and IL-15 are cytokines known for their immune-boosting properties, which are significant in melanoma treatment, particularly in modulating immune responses in regional lymph nodes (LNs), a common site for early melanoma metastasis." (PMID 40636453, 2025). "A Phase I/Ib clinical trial (NCT02452268) evaluated NIZ985, a recombinant form of IL-15 and its receptor α, as a single agent and in combination with the anti-PD-1 antibody spartalizumab in melanoma patients." (PMID 40636453, 2025). "Subsequently, the NK cells were stimulated for 5 hours under different conditions (resting, IL-12 + IL-18, IL-15, B16-melanoma cells)." (PMID 39920136, 2025).
melanoma (continued). "One study proposed electroporation to deliver a plasmid carrying human IL-15 gene directly to B16F10 melanoma nodules induced in female C57BL/6J mice, and this strategy resulted in regression of the tumor, long-term survival, lower tumor recurrence." (PMID 38164270, 2024). "For T cells it was shown that MDM2 inhibition can induce production of tumour necrosis factor α and IFN-γ, whereas in melanoma cells MDM2 inhibition induces interleukin-15 (IL-15) production." (PMID 39530091, 2024). "In vivo experiments on melanoma cell lines revealed that IL-15 induces dendritic cells to successfully prime naïve CD8+ T cells to differentiate into antigen-specific cytotoxic T cells." (PMID 38928238, 2024). "By using electroporation to deliver plasmid IL-15 into a melanoma mouse model, tumor growth was reduced and survival prolonged." (PMID 38928238, 2024). "Next, we now performed in vitro killing assays with B16 melanoma cells with a customized killing assay for B16 cells by increasing the coincubation with NK cells to 24 h and the addition of IL‐15 to ensure NK cell survival over this period." (PMID 36987917, 2023). "On the other hand, the mbIL-15 isoform which is likely to represent the predominant IL-15 isoform in melanomas was detected in all of them." (PMID 37334356, 2023). "Metastatic melanoma cell lines express a phorbol-12-myristate-13-acetate (PMA)-cleavable membrane-bound IL-15 (mbIL-15), whereas cultures from primary melanomas express a PMA-resistant isoform." (PMID 37334356, 2023). "Analysis of a melanoma tissue microarray shows a significant increase in the number of IL-15+ tumor cells from the benign nevi to metastatic melanoma stages." (PMID 37334356, 2023). "Membrane-bound and secreted IL-15/IL-15Rα complexes are continuously present during progression in melanoma." (PMID 37334356, 2023). "We demonstrated that gene-based IL-15 delivery efficiently drives immune cell-mediated melanoma cell killing." (PMID 37923822, 2023). "The expression of IL-15/IL-15Rα complexes by melanoma cells was evaluated both ex vivo and in vitro by tissue microarray, PCR, and flow cytometry." (PMID 37334356, 2023). "In this in vitro study, we demonstrated that genetically delivered IL-15/IL-15Rα modulates the composition and activation of melanoma surrounding immune cells and elicits immune cell-mediated anti-tumor immune responses." (PMID 37923822, 2023). "For instance, SC injection of B78-H1 cells that were genetically modified to express IL-12 delayed melanoma growth in mice, an effect that was enhanced by IL-15 administration." (PMID 38250068, 2023). "As a first step, we investigated the expression of IL-15 in samples of normal skin, nevi, and melanomas at different stages using a tissue microarray." (PMID 37334356, 2023). "The synergistic anticancer efficacy of CDDP and IL-15 was obtained by a single peritumoral injection of the IL-15/CDDP co-loaded hydrogel into B16F0-RFP melanoma-bearing C57BL/6 mice." (PMID 37265604, 2023). "The aim of this study is to investigate the possible role of Interleukin-15/Interleukin-15 Receptor α (IL-15/IL-15Rα) complexes in melanoma development." (PMID 37334356, 2023). "In its first dose‐escalating clinical trial, IL15 was intravenously administered for 12 consecutive days to patients with metastatic renal cell carcinoma and melanoma, and its efficacy was evident in some patients with the clearance of metastatic lesions." (PMID 35174623, 2022). "We have comprehensively demonstrated, for example, the numerous benefits of IL-15 coengineering of murine CAR T cells in a syngeneic melanoma tumor model." (PMID 35990626, 2022). "Supporting this notion, purified TCR-transgenic anti-GP100 pmel CD8+ T cells expanded in vitro with OMCPmutIL-2 were able to lyse B16 melanoma cells more readily than those expanded in IL-2 or IL-15." (PMID 35603788, 2022).
melanoma (continued). "HSC reconstituted NSG‐Tg(Hu‐IL15) mice also significantly impaired the growth of a PDX melanoma compared with NSG mice." (PMID 35959876, 2022). "CISH downregulates interleukin 15 (IL-15) signaling in natural killer cells, and Cish-/- mice injected with murine melanoma cells exhibit greatly reduced metastasis." (PMID 34067095, 2021). "The authors suggest the development of novel combinatorial immunotherapy with IL-15 and TIGIT blockade to promote NK cell-mediated destruction of MHC class I-deficient melanoma, which are refractory to CD8+ T cell-mediated immunity." (PMID 34367161, 2021). "Under the auspices of the PRECINCT Canine Trials Network the (human) IL-15 superagonist AnktivaR is being tested in combination with inhaled (human) IL-15 in dogs with melanoma or osteosarcoma driven lung metastases [PIs: Canter RJ, Rebhun RB." (PMID 34421888, 2021). "For example, in two studies using exosomes derived from NK-92 cells (one with IL-15 priming), the exosomes showed cytotoxic effects on melanoma (B16F10) and breast cancer (MDA-MB-231/F) cells that were abolished by anti-Fas antibody." (PMID 34093547, 2021). "GET has been previously used to deliver interleukin-15 (IL-15) to mouse melanoma, resulting in long-term tumor regression and the survival of a percentage of treated animals after challenge." (PMID 33096755, 2020). "A recombinant MYXV-expressing murine, IL-15 (vMyx-IL-15), was tested in an immunocompetent melanoma model." (PMID 31936317, 2020). "Previously, we demonstrated that the electrotransfer of IL-15 directly to tumors leads to the regression and long-term survival of mice with melanoma." (PMID 33096755, 2020). "Previous studies from our lab showed that IL-15 GET delivered to established tumors in a mouse melanoma model resulted in complete tumor regression." (PMID 33096755, 2020). "A correlation between high IL-15 serum levels, poor prognosis in melanoma patients, and reduced efficacy in treatment with ipilimumab was observed." (PMID 33096755, 2020). "IL-15 expression correlates with NK cell infiltration in human tumor samples, and data from a murine melanoma model indicate CD11b+Ly6ChiLy6G- monocytic cells are the major source of this cytokine." (PMID 33584718, 2020). "We show here that infected human MSCs can transfer progeny MYXV to melanoma cells and that accumulation of IL-15-expressing MYXV in murine lung lesions following delivery by MSCs can reduce tumor burden and trigger inflow of CD8+ cells." (PMID 32775618, 2020). "The therapeutic utility was also tested by the same team by demonstrating that complexed IL-15 compared to IL-15 alone, significantly reduced tumor burden in a B16 melanoma model." (PMID 31996218, 2020). "IL-15 has also been used for optimal expansion of antigen-specific T cells in vivo in melanoma models, for stem-cell-like chimeric antigen receptor T (Tscm) cells, and is crucial for persistence of inflationary MCMV-specific T cells." (PMID 31968246, 2020). "Intratumoral injection of this IL-15-armed MYXV in a subQ B16F10 melanoma model prolonged the survival of mice compared to the control, unarmed MYXV." (PMID 31936317, 2020). "Activation of the signalling pathways associated with acute phase response, granzyme B, IL15, the upstream modulator, HSP90B1 and inhibition of the upstream modulator EOMES also indicated immune related mechanisms in development of melanoma metastasis." (PMID 33142795, 2020). "In this current study, we have evaluated the delivery of interleukin-15 and its receptor in the form of plasmid DNA in a mouse melanoma model." (PMID 33096755, 2020). "Other researchers have also utilized the NDV to express interleukine-7 (IL-7) and interleukine-15 (IL-15) in their studies where the recombinant NDV strain LX/IL7/IL15 showed antitumor activity against murine melanoma cells." (PMID 33354412, 2020).
melanoma (continued). "First-in-human clinical trials using recombinant aglycosylated IL-15 produced in Escherichia coli consisted of intravenous bolus administration to patients with advanced melanoma or RCC." (PMID 30413827, 2019). "Lungs of IL-15 group showed marginal reduction in the number of melanoma lumps (65 ± 29), about 90% of that in PBS (phosphate-buffered saline) group." (PMID 29769573, 2018). "Melanoma-specific CD8 αβ T cells expand to a similar degree in high dose IL-2 (300 IU/ml) or IL-15 and produce equal amounts of IFN-γ." (PMID 28239463, 2017). "In this study, we observed that a brief culture of human CD8+ T cells with rapamycin significantly improved their survival and antitumor responses in melanoma-bearing recipients, particularly in mice treated IL-15." (PMID 26824989, 2016). "On the other hand, NK cells cultured with IL-15/IL-18 maintained their cytolytic activity against melanoma targets in the presence of both inhibitors." (PMID 27563819, 2016). "In melanoma models it was demonstrated that stimulation of effector cells with IL-15/IL-15Rα complexes or the IL-15 fusion protein RLI (composed of the N-terminal domain of IL-15Rα coupled via a linker to IL-15) significantly reduced tumor burden." (PMID 27821119, 2016). "Consistent with this, we have shown that tumor rejection is enhanced in IL-15−/−RAG−/− mice and that recurrence of melanoma is less when compared to IL-15 wild type controls." (PMID 26981246, 2016). "Adoptive transfer of in vitro expanded MART-1-TCR+CD8+ T cells induced potent antitumor responses that were further enhanced by IL-15 treatment in melanoma-bearing recipients." (PMID 26824989, 2016). "Recently, we have identified in metastatic LN a new subset of mature CD56brightCD16+ NK cells that display cytotoxic activities against melanoma cells following IL-2 or IL-15 stimulation." (PMID 26218530, 2015). "IL-15 alone or in combination with IL-2 has been used successfully in cultures of tumor-infiltrating αβT cells isolated from melanoma and Merkel cell carcinoma patients." (PMID 25101086, 2014). "Phase I trials testing IL-15 are underway in a number of solid tumors, including melanoma, RCC, NSCLC, and squamous head and neck cancers." (PMID 25268164, 2014). "Preclinical studies have shown increased potency of antigen-specific T-cells cultured with IL-15 in melanoma and plasmacytoma." (PMID 25268164, 2014). "Overall, our findings document that γδT cells in PBMC from melanoma patients responded well to zoledronate plus IL-2/IL-15." (PMID 25101086, 2014). "Our previous studies have shown that these myxoma viruses (vMyx-tdTr and vMyx-IL15-tdTr) productively infect cancer cells in vitro, but have limited effect on tumor progression of murine melanoma in immune competent mice in vivo." (PMID 25329832, 2014). "We confirmed that the vMyx-IL15Rα-tdTr virus has the same ability to infect melanoma cells as the previously characterized vMyx-tdTr control virus, and that it secretes biologically active IL15Rα-IL15." (PMID 25329832, 2014). "CD8+ T cells obtained from IL-21 aAPC-expanded melanoma TIL cultures exhibited significantly higher cytotoxic activity compared with CD8+ T cells obtained from IL-15 and IL-2 aAPC expanded TIL." (PMID 23402380, 2013). "IL-15 is being tested in patients as a monotherapy for melanoma and renal cell carcinoma in a dose escalating clinical trial (NCT01021059)." (PMID 23285013, 2012). "We chose melanoma as model entity for the investigation of the oncolytic effects and IL-15 expression induced by the delNS1-IL-15 virus." (PMID 22563505, 2012). "In conclusion, the present study describes the generation of an IL-15-armed oncolytic delNS1 virus and delineates the molecular mechanisms by which delNS1 viruses including delNS1-IL-15 exert oncolytic effects in human melanoma cells." (PMID 22563505, 2012).